JUNB (JunB proto-oncogene, AP-1 transcription factor subunit)
Diseases named in the same sentence as JUNB in open-access papers (continued):
Sharing a sentence is not in itself a finding about the gene and the disease.
Autoimmunity (7 papers, 2017 to 2023). The occurrence of an immune reaction against the organism's own cells or tissues. "JunB is critical for accumulation and suppressive functions of eTreg cells, and Treg-specific ablation of JunB results in multi-organ autoimmunity." (PMID 30559442, 2018). "Although dispensable for homeostatic Th17 cell development, JunB is required for induction and maintenance of Th17 effector responses in the inflammatory contexts of both acute infection and chronic autoimmunity in mice." (PMID 28824171, 2017). "Taken together, the in vivo findings identify an absolute and selective requirement for JunB in the induction and maintenance of Th17 effector cells during inflammation, in the context of both chronic autoimmunity and acute infection." (PMID 28824171, 2017). "In addition, we have provided a comprehensive overview of JunB in autoimmunity and immunosuppression." (PMID 37731821, 2023). "JunB facilitates the binding of IRF4 to a subset of its transcriptional target sites, like CTLA4 and ICOS, and Treg-specific deficiency in JunB results in multiorgan autoimmunity." (PMID 34631704, 2021). "In addition, it has been demonstrated that JUNB promotes Th17 cells’ development, but inhibits T regulatory cells’ fate during chronic autoimmunity." (PMID 31382516, 2019). "Therefore, the regulation of JunB on the immune microenvironment depends on its preferential transcriptional regulation of the immune effectors across different cells, thereby potentially playing significant roles in autoimmunity and immunosuppression." (PMID 37731821, 2023). "The present study provides genetic evidence that JunB is required for Th17 cell differentiation: Junb-deficient CD4+ T cells are defective in differentiating into Th17 cells, and Junb-deficient mice are refractory to induction of the Th17 cell-dependent autoimmunity EAE." (PMID 29234109, 2017). "Mice lacking JunB in Treg cells develop multi-organ autoimmunity, concomitant with aberrant activation of T helper cells." (PMID 30559442, 2018).
Hodgkins lymphoma (7 papers, 2019 to 2023). A heterogeneous group of malignant lymphoid neoplasms of B-cell origin characterized histologically by the presence of Hodgkin and Reed-Sternberg (HRS) cells in the vast majority of cases. "In Hodgkin’s lymphoma, JunB can bind to an enhancer region of the PD-L1 promoter, facilitating PD-L1 expression." (PMID 38038129, 2023). "Alternatively, for the regulation of co-inhibitory ICs expression, it was observed in Hodgkin’s lymphoma that AP-1 complex, consisting of c-Jun and JunB, can bind to the enhancer regions of the PD-L1 promoter." (PMID 33291616, 2020). "Moreover, c-JUN and JUNB transcription factors reportedly promote the proliferation of classical Hodgkin’s lymphoma tumor cells through the transport of G proteins." (PMID 36978180, 2023). "c-Jun forms the AP-1 complex with JunB and has a hyperactivity in Hodgkin lymphoma cells." (PMID 35402280, 2022).
renal cell carcinoma (7 papers, 2015 to 2025). "A separate group of studies has investigated the roles and functions of JUNB in Von Hippel–Lindau syndrome, a genetic condition with a strong correlation to certain tumors, including pheochromocytoma and renal cell carcinoma." (PMID 41020863, 2025). "Studies of solid tumors also demonstrated JUNB as a potential target in renal cell carcinoma, cervical cancer, endometrial cancer and colorectal cancer, while its role in GC is not yet clear." (PMID 37337631, 2023). "It has been well-documented that JUNB participates in tumorigenesis, progression, and invasion of several tumors like renal cell carcinoma and hepatocellular carcinoma as well as inhibition of the proliferation of adaptive immune cells." (PMID 35812726, 2022). "JUNB has been reported several times in renal cell carcinoma (RCC)." (PMID 41020863, 2025). "Additionally, the ability of JunB to promote renal cell carcinoma cell invasion has been reported, and knockdown of JunB expression by shRNA greatly inhibited the invasiveness of the cells." (PMID 25938468, 2015). "Moreover, preclinical studies have indicated a key role for JunB as a critical activator of AFs, VEGF in particular, in breast cancer, renal cell carcinoma, and teratocarcinoma." (PMID 34007044, 2021). "In contrast to other cancers such as renal cell carcinoma, we did not observe a correlation between JUNB, MMP2, and MMP9 expression, highlighting the dependency of JunB transcriptional programs on the tumor cell type." (PMID 34007044, 2021).
autoimmune disease (6 papers, 2017 to 2023). A disorder resulting from loss of function or tissue destruction of an organ or multiple organs, arising from humoral or cellular immune responses of the individual to their own tissue constituents. "Noteworthily, JunB promotes the progression of Th2-mediated autoimmune diseases, such as asthma and skin allergy, and Th17-mediated autoimmune encephalomyelitis and colitis." (PMID 37731821, 2023). "It has been shown that STAT3 binds to the promoter of JUNB to induce inflammation and promote the progression of autoimmune diseases." (PMID 34926700, 2021). "In this study, we found evidence of previously unidentified functions of FRA1 and JUNB in Th17 cell differentiation and autoimmune disease." (PMID 29326694, 2017). "In conclusion, our results suggest a previously unidentified function of FRA1/JUNB in T-cell-mediated autoimmune diseases." (PMID 29326694, 2017). "Our identification of the involvement of FRA1/JUNB in T-cell development provides a potential therapeutic target for the treatment of autoimmune diseases." (PMID 29326694, 2017). "Therefore, JunB is essential for the survival and differentiation of Th2 cells and Th2-mediated autoimmune diseases." (PMID 37731821, 2023). "Aberrant expression of JunB is frequently observed in autoimmune diseases, wherein it may contribute to the enhancement of Th cell differentiation and the release of pro-inflammatory factors." (PMID 37731821, 2023). "The selective requirement of JunB for IL-23-dependent TH17 pathogenicity suggests that the JunB-dependent pathway may be a therapeutic target for autoimmune diseases." (PMID 28555647, 2017).
colitis (6 papers, 2015 to 2023). Inflammation of the colon. "Due to the biased expression of JunB in intestinal Tregs and observed weight loss in KO animals (a common manifestation of colitis), we evaluated CD4+ T cells for evidence of colonic cytokine dysregulation." (PMID 32296416, 2020). "To assess whether JunB is also required for other TH17-mediated diseases, we investigated the function of JunB in colitis development by transferring Junb-deficient CD4+CD45RBhiCD25− T cells into Rag1-deficient mice." (PMID 28555647, 2017). "In addition, due to the damage of Treg differentiation, the conditional knockout of JunB in mouse CD4+ T cell is more susceptible to colitis induced by dextran sulfate sodium (DSS), and deficiency of JunB in vitro CD4+ T cells resulted in the failure of IL-2-induced Treg cell differentiation." (PMID 37731821, 2023). "However, JunB is required for generation of pathogenic TH17 cells in EAE and colitis models." (PMID 28555647, 2017). "IL-2 promoted Treg cell development via AP-1 transcription factor JunB, and injection of IL-2–anti-IL-2 antibody complex in JunBfl/fl Cd4-Cre mice expanded Treg cells and alleviated DSS-induced colitis." (PMID 35237152, 2022). "Furthermore, we show that JunB is essential for pathogenicity of TH17 cells in EAE and colitis models, but it is not required for generation of non-pathogenic, gut-resident TH17 cells." (PMID 28555647, 2017).
leukemia (6 papers, 2007 to 2023). A malignant (clonal) hematologic disorder, involving hematopoietic stem cells and characterized by the presence of primitive or atypical myeloid or lymphoid cells in the bone marrow and the blood. "This strategy was designed to uncover genes involved in the initial steps of HSC transformation caused by loss of JunB expression, which in turn mediates the early phase of leukemia development." (PMID 20098702, 2010). "Loss of JunB function in HSC causes an aberrant stem cell expansion leading to MPD development and eventually frank leukemia." (PMID 20098702, 2010). "However, more clinical studies and long-term follow-up are needed, and the intrinsic mechanisms of JunB in leukemia needs to be revealed." (PMID 37731821, 2023). "While c-Jun is an oncogene overexpressed or amplified in different types of cancer, including sarcomas, it has been demonstrated that conditional JunB inactivation or PU.1 related downregulation of both JunB and c-Jun provoke myeloproliferative disorders and different types of leukemia in mice." (PMID 23966864, 2013). "Up-regulated DNMTs may contribute to the pathogenesis of leukemia by inducing aberrant regional hypermethylation of tumor suppressor genes such as p73, JunB, p16, p57kip2, 14-3-3 and BRCA-1." (PMID 17407586, 2007). "Lentivirus-mediated JunB repair can make NOD-SCID mice lose their self-renewal ability and inhibit the progress of leukemia." (PMID 37731821, 2023). "In leukemia cells HL-60, THP-1, and samples of acute myeloid leukemia patients, DCF induced apoptosis through activator protein-1 (AP-1) transcription factors (c-Jun, JunB, and Fra-2), induction of growth arrest and DNA damage-45α protein (GADD45α), and activation of c-Jun N-terminal kinase (JNK)." (PMID 34064702, 2021).
lung adenocarcinoma (6 papers, 2012 to 2025). A carcinoma that arises from the lung and is characterized by the presence of malignant glandular epithelial cells. "In summary, our results suggest that DMSO is an important stimulator of the tumor suppressor protein HLJ1 through JunB and JunD activation in the highly invasive lung adenocarcinoma CL1–5 cells." (PMID 22529897, 2012). "To this end, we utilized the lung adenocarcinoma cell line A549 and, following the same experimental strategies as in MCF10A cells, generated A549 JUNB WT and mut cell clones as well as mixed populations of A549 control and JUNB-ER-expressing cells." (PMID 36672507, 2023). "By integrating two time-course microarray data in human lung adenocarcinoma cells, we specifically have identified some nested gene clusters and found that TGFB1, EGR1, EGR2, EGFR, IL6, JUN, and JUNB all are involved in these clusters." (PMID 28959347, 2017). "For instance, in lung adenocarcinoma cells, METTL3, through its m6A methyltransferase activity, mediates the m6A modification of JUNB mRNA, which enhances mRNA stability and promotes its nuclear translocation as a transcription factor to activate downstream gene expression." (PMID 40299340, 2025).
myeloproliferative disease (6 papers, 2010 to 2024). "Though junB–/– Ubi-junB mice escaped from embryonic lethality, they developed a transplantable myeloproliferative disease eventually progressing to blast crisis, resembling human CML." (PMID 37731821, 2023). "By reintroduction of JunB expression under the ubiquitin promoter (Ubi-JunB) in JunB−/− mice (junB−/− −Ubi-JunB) embryonic lethality of JunB−/− mice was rescued but these mice developed a myeloproliferative disease." (PMID 34736527, 2021). "Conditional knock-out of JUNB in hematopoietic stem cells leads to the development of a myeloproliferative disease whereby the target cell of the gene editing event is of the essence for the phenotype, again indicating the cell-type specificity of AP-1 function." (PMID 39506987, 2024).
non-small cell lung carcinoma (6 papers, 2013 to 2025). A group of at least three distinct histological types of lung cancer, including non-small cell squamous cell carcinoma, adenocarcinoma, and large cell carcinoma. "In the present study, we investigated the expression of JUNB and CXCR4 in circulating tumor cells (CTCs) of non-small-cell lung cancer and small-cell lung cancer patients and determined their clinical significance." (PMID 36612166, 2022). "In non-small cell lung cancer, SE promote TGFβ-induced EMT by enhancing the expression of EMT-related transcription factors, while a BRD4-specific inhibitor JQ1 can inhibit SE-driven transcription of ETS2, HNF4A, JUNB, and other genes, resulting in the obstruction of EMT process." (PMID 39915455, 2025).
ovarian carcinoma (6 papers, 2013 to 2025). A malignant neoplasm originating from the surface ovarian epithelium. "The amplification of JUNB was associated with a worse outcome in ovarian cancer patients, while the gene MSLN, prevalent in C3 FN1+ TCs, was previously thought to have a role in the peritoneal dissemination of ovarian TCs." (PMID 40612060, 2025). "Moreover, tumor genomic data indicate that JUNB amplification associates with poor prognosis in breast and ovarian cancer patients." (PMID 36494864, 2022). "Additionally, tumor genomic data suggest that JUNB amplification correlates with poor prognosis in ovarian cancer patients." (PMID 40612060, 2025). "Moreover, breast and ovarian cancer patients with high JUNB levels due to gene amplification showed poorer prognosis than the rest of patients." (PMID 36494864, 2022). "We will further study the interaction between JUND/JUNB and MUC5B in vivo and in vitro to uncover the mechanism of chemotherapy sensitivity in ovarian cancer." (PMID 32441484, 2020). "Furthermore, GEPIA database analysis showed that only four genes, PIK3R1, JUNB, RHOBTB2, and SLC25A37, were expressed at low level in ovarian cancer and were correlated positively with YTHDC1." (PMID 37781028, 2023).
viral infection (6 papers, 2018 to 2024). "As JunB is a transcription factor, we hypothesized that the absence of JunB may alter the expression of host factors required for viral infection, such as CD4 or CXCR4." (PMID 38835488, 2024). "To confirm that the decrease in CXCR4 expression was specifically responsible for the lack of X4-tropic viral infection in JunB KO 1–6 cells, we recovered CXCR4 expression by transfection of a CMV-driven CXCR4 expression plasmid." (PMID 38835488, 2024).
chronic myeloid leukemia (5 papers, 2007 to 2023). "JunB serves as a causative factor in the development of chronic myeloid leukemia." (PMID 17407586, 2007). "For example, abnormally low expression of JunB in peripheral blood of patients with chronic myeloid leukemia (CML) was found to be attributed to DNA methylation of JunB promoter." (PMID 37731821, 2023). "Jun B transgenic mice lost its expression in myeloid lineage resulting in chronic myeloid leukemia, indicating that JunB acts as a tumor suppressor gene in myeloid cells." (PMID 17407586, 2007). "Notably, patients with acute or chronic myeloid leukemia presented low expression levels of JunB, increasing studies suggested JunB affect cell cycle and differentiation through transcriptionally activating essential genes." (PMID 37731821, 2023). "JunB was also reported to have tumor suppressor function in chronic myeloid leukemia and B cells." (PMID 22443687, 2012).
hepatocellular carcinoma (5 papers, 2015 to 2025). A malignant tumor that arises from hepatocytes. "Next, we explored the phenomenon associated with JUNB overexpression in epithelial hepatoma cells, and its role in the acquisition of metastatic potential." (PMID 40253402, 2025). "Immunostaining of subcutaneous tumors induced with Tig3-20 and hepatoma cells revealed the presence of JUNB-positive cells around the tumor nodules." (PMID 40253402, 2025). "These factors may also increase the rate of JUNB-mediated transformation into CD90-positive hepatoma cells." (PMID 40253402, 2025). "The conversion rate of epithelial hepatoma cells with high JUNB expression to CD90 positive cells upon treatment with purified TGFb1 was significantly increased compared with that in untreated cells, being 7.51% for Huh1, 10.5% for Huh7, and 10.7% for patient HCC." (PMID 40253402, 2025). "By increasing the expression of JUNB in epithelial hepatoma cells, we could elucidate a part of the signaling pathway that renders the tumor environment conducive to the formation of CD90-positive CSCs." (PMID 40253402, 2025). "In addition, the JUNB expression in EpCAM-positive hepatoma cells was increased by paracrine stimulation with fibroblast-derived TGFb1." (PMID 40253402, 2025). "However, the upstream pathway that increases the expression of JUNB in epithelial hepatoma cells remains unknown." (PMID 40253402, 2025).
myocardial ischemia (5 papers, 2009 to 2025). A disorder of cardiac function caused by insufficient blood flow to the muscle tissue of the heart. "Their monitoring to identify possible episodes of early myocardial ischemia by dosing new markers that have proven their usefulness such as Cx43, JunB, and TUNEL assays could represent a turning point in the prevention of SCD." (PMID 39851472, 2025). "During myocardial ischemia or reperfusion, the expression of many genes such as c-fos, c-jun, junB, Egr-1, and HSP70 is upregulated, and some of them are considered to be involved in the endogenous cardioprotection against myocardial ischemia/reperfusion injury." (PMID 25397408, 2014). "However, another study demonstrated that during early myocardial ischemia (EMI), JUNB increases in the nuclei of cardiomyocytes in both in vivo models and in human myocardium." (PMID 39712244, 2024). "During myocardial ischemia or reperfusion, many genes such as c-fos, c-jun, junB, Egr-1, HSP70 can be up-regulated, and some of these myocardial genes have been considered to be involved in the endogenous cardioprotection against myocardial ischemia-reperfusion injury." (PMID 19333417, 2009).
Sepsis (5 papers, 2016 to 2025). Sepsis is defined as life-threatening organ dysfunction caused by a dysregulated host response to infection. "Differential expression in Th17 cells in sepsis compared to controls identified downregulation in genes associated with T cell activation, differentiation (JUNB; -0.90log2FC), and inflammatory pathways, including NF-κB signalling." (PMID 41208955, 2025). "JNK is activated during sepsis and phosphorylates the N-terminal transcriptional activation domains (TADs) of Jun family members, such as c-Jun, JunB, and JunD." (PMID 27011790, 2016). "Among the upregulated DEGs in E-SEP compared to Y-SEP, we observed inflammation-associated genes, such as FOSB, DUSP1, and JUNB, and aging-associated genes, such as IFN-stimulated genes DDIT4 and DUSP2, thereby indicating an overactive inflammatory response of cDCs in elderly patients with sepsis." (PMID 38909272, 2024). "However, only a small part of MVPs have relatively large Δβ (|Δβ|> 0.2), and focusing on those with large Δβ, we found that 6 of 26 differentially methylated genes (23.1%) were previously associated with sepsis in the literature, including ALK, ZEB2, MNDA, AIM2, TLR5, and JUNB." (PMID 35242787, 2022). "Both JUNB and FOSL2 were identified as sepsis MR candidates common to RA and MS." (PMID 34680414, 2021).